GRTP1 (growth hormone regulated TBC protein 1)
Description:
May act as a GTPase-activating protein for Rab family protein(s).
Synonyms: TBC1D6; FLJ22474
Tractability: Antibody: its Gene Ontology location is reachable by antibodies, with medium confidence. PROTAC: ubiquitination databases record sites on it; its protein half-life has been measured.
Gene: Protein-coding gene on chromosome 13 (113,324,163 to 113,364,158, reverse strand). Ensembl gene ENSG00000139835.
Gene Ontology:
Molecular function: GTPase activator activity
Cellular component: cytoplasm; plasma membrane
Genetic constraint (gnomAD): Loss-of-function variants: 55 observed, 41.42 expected, observed/expected ratio (o/e) 1.33, 90% interval 1.07 to 1.66. The upper end of that interval is the gene's LOEUF score, 1.66, which puts it in group 6 of 6, group 1 being the genes least tolerant of losing a copy. Missense variants: 489 observed, 448.66 expected, observed/expected ratio (o/e) 1.09, 90% interval 1.01 to 1.17. Synonymous variants: 212 observed, 187.28 expected, observed/expected ratio (o/e) 1.13, 90% interval 1.01 to 1.27.
Homologues: Orthologues: macaque GRTP1 (96% identical), chimpanzee GRTP1 (92% identical), mouse Grtp1 (85% identical), dog GRTP1 (83% identical), pig GRTP1 (82% identical), guinea pig GRTP1 (80% identical), zebrafish grtp1a (69% identical), zebrafish grtp1b (61% identical), tropical clawed frog grtp1 (61% identical). Paralogues in human: TBC1D10B (31% identical), TBC1D10A (29% identical), TBC1D2 (29% identical), TBC1D2B (29% identical), TBC1D10C (28% identical), TBC1D1 (26% identical), TBC1D9 (26% identical), TBC1D9B (26% identical), EVI5 (25% identical), TBC1D8 (24% identical), EVI5L (24% identical), TBC1D4 (23% identical), and 33 more.
Diseases named in the same sentence as GRTP1 in open-access papers:
GRTP1 is named in the same sentence as 5 diseases in open-access papers, as found by Europe PMC text mining. Sharing a sentence is not in itself a finding about the gene and the disease. The quoted sentences say what the papers report.
gastric cancer (1 paper, 2022). A primary or metastatic malignant neoplasm involving the stomach. "We found that high expression of CPVL, ONECUT2, DDC, PRSS21, and GRTP1 increase the risk of gastric cancer." (PMID 35754804, 2022). "The high risk-scores of CPVL, ONECUT2, DDC, PRSS21, and GRTP1 could be used to determine the degree of malignancy and prognosis in gastric cancer patients." (PMID 35754804, 2022). "To find out the role of hub genes in the overall survival of gastric cancer we performed a multivariate Cox regression analysis, among 21 hub genes, the eight genes (KCNJ3, CPVL, ONECUT2, SLC19A3, DDC, PRSS21, F12, and GRTP1) were designated as independent indicators of poor prognosis." (PMID 35754804, 2022).
glioma (1 paper, 2019). A benign or malignant brain and spinal cord tumor that arises from glial cells (astrocytes, oligodendrocytes, ependymal cells). "Evaluation of the GRTP1-Plk interaction utilizing the STRING database molecular action function indicated a regulatory role for GRTP1, suggesting the need for further investigation of GRTP1 as a potential target for anti-glioma therapy." (PMID 31475119, 2019). "ECEL1 and GRTP1 did not demonstrate significant downregulation in any of the subtypes of human glioma." (PMID 31475119, 2019).
Tinnitus (1 paper, 2024). Tinnitus is an auditory perception that can be described as the experience of sound, in the ear or in the head, in the absence of external acoustic stimulation. "The most downregulated genes in the tinnitus (when compared to the non-tinnitus group) were LOC103690064, AABR07048397.1, Trpv1, AABR07061378.1, Ncaph, Spata20, Rps19, Enpp3, Grtp1, and Glra1." (PMID 38562529, 2024).
GRTP1 also shares sentences with these, for which no sentence is quoted: autoimmune thyroid disease (1 paper); tumor (1).